CARM1 (coactivator associated arginine methyltransferase 1)
Diseases named in the same sentence as CARM1 in open-access papers (continued):
Sharing a sentence is not in itself a finding about the gene and the disease.
breast carcinoma (continued). "To determine if CARM1 might be involved in the development of specific breast tumor subtypes we have measured the CARM1 expression levels, in adjacent-normal and tumor tissues from a cohort of over 500 breast cancer patients from the US (Chicago, IL) and Nigeria, Africa." (PMID 23663560, 2013). "Our finding that CARM1 overexpression in breast cancer correlated with high HER2 expression supports the hypothesis that CARM1 might play an important role in the regulation of the HER2 pathway, probably through transcriptional coactivation with the p160 family." (PMID 23915145, 2013). "CARM1 methylates the SWI/SNF subunit BAF155 at arginine-1064, directing it to oncogenic c-Myc targets and promoting breast cancer metastasis." (PMID 41516402, 2026). "In a separate study, the same authors demonstrated that CARM1 methylates MED12 and that methylation of MED12 sensitizes breast cancer lines to chemotherapy." (PMID 41516402, 2026). "Knockdown of CARM1 and GATAD2A significantly attenuates breast cancer cell growth both in vitro and in vivo." (PMID 38676947, 2024). "Through selective splicing, CARM1 manifests in several isoforms, including the full-length variant (referred to as CARM1) that is predominantly expressed in healthy heart, brain, testis, and skeletal muscle, and the truncated CARM1 lacking exon 15 (CARM1ΔE15) that prevails in breast cancers." (PMID 38619752, 2024). "Both CARM1 and GATAD2A were found to be expressed higher in breast tumor than normal samples, and their high expression predict poor prognosis in breast cancer patients." (PMID 38676947, 2024). "We and others have previously shown that epigenetic coregulators such as ZMYND8, CHD4, CARM1, TRIM24, and JMJD2C are frequently amplified or upregulated to promote breast cancer progression through their role in epigenetic reprogramming." (PMID 37655663, 2023). "This retrospective study analyzes the expression of TFEB, CARM1, SIRT1, and Beclin-1 and the methylation of PITX2 in breast carcinoma." (PMID 34663249, 2021). "CARM1 works by arginine methylation of proteins, which can mediate BAF155 and MED12 methylation to affect breast cancer chemoresistance." (PMID 33495408, 2021). "In high-grade breast tumors, the mRNA levels of CARM1 and ACTR are elevated, indicating an oncogenic role of CARM1 in breast cancer." (PMID 34006904, 2021). "Previous studies have emphasized the importance of CARM1 in resistance to chemotherapy through methylating RNA polymerase II mediator complex subunit 12 (MED12), resulting in highly aggressive breast cancer that insensitive to drugs." (PMID 32487779, 2020). "Collectively, the chemical probe SKI-73 (6a) alters the epigenetic plasticity of MDA-MB-231 breast cancer cells via the combined effects of SKI-73(6a)’s molecular scaffold and specific inhibition of CARM1’s methyltransferase activity." (PMID 31657716, 2019). "Few studies have looked at these modifications on SWI/SNF; however, in breast cancer, methylation of BAF155 by CARM1 is important for SWI/SNF activity in metastatic progression." (PMID 29273066, 2017). "Previous research appeared to support the argument that CARM1 is oncogenic in that the reduction of CARM1 expression decreased E2F1 levels and cell cycle progression in MCF7 breast cancer cells." (PMID 26030442, 2015). "Using the zinc finger nuclease technique, CARM1 knockout clones were generated for the MCF7 and MDA-MB-231 breast cancer models and the HEK293T kidney cell line and were validated as CARM1 dysfunctional." (PMID 25927994, 2014). "The Western blot analysis showed that CARM1 expression levels, in some selected colorectal cells, was high, and compatible with the MDA-MB-231 breast cancer cells, in most colon cancer cells except for HT-29." (PMID 20462455, 2010).
breast carcinoma (continued). "Certain circRNAs identified in our analysis demonstrated exceptionally strong discriminatory power across breast cancer subtypes, e.g., hsa_circRNA_104310 (host gene: ZDHHC4), hsa_circRNA_404935 (ZBTB16), hsa_circRNA_003641 (ATM), and hsa_circRNA_102445 (CARM1)." (PMID 41516402, 2026). "CARM1-mediated methylation of MED12 sensitizes breast cancer cells to 5-fluorouracil but not to RTK inhibitors, suggesting a unique mechanism of drug response modulation in breast cancer compared with NSCLC." (PMID 40833497, 2025). "Additionally, the data in GSE65194 showed that PRMT1, PRMT3, CARM1, PRMT5, and PRMT6 were highly expressed in basal-like breast cancer." (PMID 38476024, 2024). "In breast cancer cells, methylation of the key glycolytic enzyme pyruvate kinase M2 isoform (PKM2) by CARM1 shifts the metabolic balance from oxidative phosphorylation to aerobic glycolysis, producing a large amount of ATP, so as to promote tumor cell proliferation and migration." (PMID 35033016, 2022). "This study’s main objective is to assess the prognostic role of TFEB, CARM1, SIRT1, and Beclin-1 in chemo-treated breast carcinoma and compare the TFEB, CARM1, SIRT1, and Beclin-1 expression with the methylation of PITX2 in breast cancer treated with chemotherapy." (PMID 34663249, 2021). "We first asked whether CARM1 is required for estrogen/ERα-induced gene transcriptional activation by transcriptomics analysis in MCF7, an ERα-positive breast cancer cell line." (PMID 32206101, 2020). "Such compounds were evaluated in p300, PCAF, SIRT1/2, EZH2 and CARM1 enzyme assays, and in NB4 APL, U937 AML, MCF-7 breast cancer and SH-SY5Y neuroblastoma cells, to determine their effects in cell cycle phases and apoptosis induction when used at 5 μM for 30 h." (PMID 32650558, 2020). "Compounds 4a–n have been evaluated in p300, PCAF, SIRT1/2, EZH2 and CARM1 enzyme assays, and in NB4 human acute promyelocytic leukemia (APL), U937 AML, MCF-7 breast cancer and SH-SY5Y neuroblastoma cells, to determine their effects in cell cycle phases and apoptosis (sub-G1 peaks) induction." (PMID 32650558, 2020). "Collectively, the effects of CARM1 chemical probes are highly context-dependent, with SKI-73 (6a) having different uses in impairing the invasiveness of breast cancer cells, while TP-064 and EZM2302 have uses in preventing the proliferation of hematopoietic cancer cells." (PMID 31657716, 2019). "Genetically modifying cells so they will not produce any CARM1 stops the spread of breast cancer cells, but developing a drug with the same effects has proved difficult." (PMID 31657716, 2019). "Mechanistically, CARM1 methylates Arg1064 of BAF155 and thus facilitates the recruitment of the BAF155-containing SWI/SNF complex to a specific subset of gene loci that are essential for breast cancer metastasis." (PMID 31657716, 2019). "CARM1 is overexpressed in a variety of cancer types, has been identified as an oncogenic client protein of Hsp90 in K562 leukemia cells and regulates tumor metastasis by methylation of BAF155 in MDA-MB-231 breast cancer cells." (PMID 26030442, 2015). "Although it is known to be an ER cofactor in breast cancer, CARM1 expression levels are independent of ER." (PMID 23663560, 2013). "The tissue microarray showed that CARM1 was particularly overexpressed in the colorectal cancers while CARM1 expression was not prevalent in the prostate and breast cancers." (PMID 20462455, 2010). "In cultured cancer cells, mRNA and protein level of CARM1 were not always correlated, especially in 231 breast cancer cells and CWR22RV PCa cells." (PMID 20462455, 2010). "To enable high-throughput screening for CARM1 degraders, we generateda HiBiT-CARM1 cell line using CRISPR/cas9-mediated knock-in technology.The HiBiT tag was inserted at the N-terminus of endogenous CARM1 inestrogen receptor-positive breast cancer cell line MCF7." (PMID 41453375, 2026).
breast carcinoma (continued). "The functional role of CARM1-mediated GATAD2A methylation in breast cancer cell growth prompted us to examine whether targeting CARM1-mediated GATAD2A methylation using CARM1 inhibitors, EZM2302 and TP-064, could inhibit breast cancer cell growth." (PMID 38676947, 2024). "Moreover, co-activator associated arginine methyltransferase 1 (CARM1, also known as PRMT4) is overexpressed in metastatic breast cancer as opposed to normal breast tissues." (PMID 35216622, 2022). "More importantly, there is no additive effect upon combining CARM1-KO with SKI-73 (6a) treatment, underlying the fact that the two orthogonal approaches target the commonly shared pathway(s) that are essential for the invasion of breast cancer cells." (PMID 31657716, 2019). "On the other hand, this correlation is lost in the case of the basal-like subtype, so that in the breast cancer luminal subtypes, we can deduce that both TFEB and CARM1 act in the same pathway, while this may not be true in the case of the basal-like molecular subtype." (PMID 34663249, 2021).
colorectal cancer (20 papers, 2010 to 2025). A primary or metastatic malignant neoplasm that affects the colon or rectum. "In colorectal cancer, coactivator-associated arginine methyltransferase CARM1 methylates arginine 339 (R339) of ACSL4, promotes the binding of RNF25 to ACSL4 and its ubiquitination, inhibits ferroptosis of tumor cells, and effectively attenuates ferroptosis-related cancer immunotherapy." (PMID 40050614, 2025). "Feng's research group has shown that inhibiting CARM1‐mediated methylation of ACSL4 can promote ferroptosis in colorectal cancer." (PMID 39964832, 2025). "Mechanistically, RPF2 expression facilitates the binding of the RPF2‐CARM1‐MYCN trio and CARM1's association with the nucleus, which in turn boosts the expression of the downstream protein ABCB1, enhancing colorectal cancer resistance." (PMID 39964832, 2025). "A report indicates that ACSL4 is methylated at the R339 site through ADMA modification by CARM1, which suppresses ferroptosis in colorectal cancer cells." (PMID 40756764, 2025). "Zhang's group discovered an upregulation of CARM1 expression in colorectal cancer tissues, which promotes cell growth both in vitro and in vivo and is directly targeted by miR‐195‐5p." (PMID 39964832, 2025). "Lastly, miR-195 targets PRMT4/CARM1 in colorectal cancer, and miR-155 regulates JMJD1A in nasopharyngeal carcinoma." (PMID 40761244, 2025). "During colorectal cancer cell growth, CARM1 interacts with β‐catenin and positively regulates gene expression mediated by β‐catenin." (PMID 39964832, 2025). "The identification of miR‐195‐5p and CARM1 as potential independent prognostic factors for colorectal cancer is a novel discovery." (PMID 39964832, 2025). "miR-195 is an antitumor element and increases radiosensitivity in colorectal cancer cells as a result of PRMT4/CARM1 targeting." (PMID 35087589, 2022). "The result shows that all cancers expressed CARM1, with the highest expression level in ovarian cancer, followed by endometrial cancer and colorectal cancer." (PMID 35033016, 2022). "Except for KIRC and KICH, CARM1 was shown to be substantially more expressed in most cancer types, which was consistent with the previous study in lung and colorectal cancers." (PMID 34745258, 2021). "The cell proliferation results indicated knockdown either Max, CARM1 or p300 significantly inhibited the growth of colorectal cancer cells to a comparable level in c-Myc-knockdown cells." (PMID 32140074, 2020). "The results of this study demonstrated that expression of CARM1 was especially high in colorectal cancers, over 75%." (PMID 20462455, 2010). "Here, we show that CARM1 overexpression was surprisingly prevalent in colorectal cancers while only a fraction of tumors from the breast and prostate overexpressed CARM1." (PMID 20462455, 2010). "The results of this study suggest that, in addition to its role in activation of steroid receptors, CARM1 functions as a transcriptional modulator by altering the activity of many transcriptional factors, especially with regard to androgen independent PCa and colorectal cancers." (PMID 20462455, 2010). "In colorectal cancer cells, CARM1/PRMT4 was reported to be an important positive regulator of Wnt/β-catenin-dependent signaling, a developmentally active pathway, well investigated in lung cancer biology." (PMID 23202904, 2012). "Further studies using surgical specimens demonstrated that CARM1 was highly overexpressed in 75% of colorectal cancers (49 out of 65) but not in the androgen-independent PCa." (PMID 20462455, 2010).
colorectal cancer (continued). "The reduced expression of CARM1 seen in responders at all stages of colorectal cancer compared with non-responders might reflex reduction in Wnt signaling reducing chemoresistance making the cells more susceptible to FOLFOX." (PMID 38304289, 2023).
ovarian carcinoma (19 papers, 2010 to 2025). A malignant neoplasm originating from the surface ovarian epithelium. "This study suggests that high levels of NAC1 and CARM1 are associated with poor prognosis in ovarian cancer patients receiving adjuvant chemotherapy, providing a new direction for prognostic biomarkers predicting chemotherapy resistance in ovarian cancer." (PMID 39964832, 2025). "The present study reveals that NAC1 associates with CARM1 in a 300–500 kDa protein complex in ovarian cancer cells." (PMID 29983869, 2018). "In a recent study, immunocompromised mice that received orthotopic injection of Coactivator-Associated Arginine Methyltransferase 1 (CARM1)-high ovarian cancer cells showed enhanced therapeutic responses to the IRE1α RNase inhibitor B-I09 compared to mice with CARM1-low ovarian tumors." (PMID 41372991, 2025). "demonstrate that CARM1 facilitates ovarian cancer growth by transcriptionally reprogramming fatty acid metabolism, leading to the production of monounsaturated fatty acids." (PMID 39964832, 2025). "Specially, a study reported that the combination of EZH2 inhibitors and PARP1 inhibitors enhanced lethality in homologous recombination (HR)-proficient and CARM1-high ovarian cancer." (PMID 40661778, 2025). "Karakashev's research group found that EZH2 inhibitors are effective in treating epithelial ovarian cancer with high expression of CARM1." (PMID 39964832, 2025). "show that targeting the IRE1α/XBP1S pathway can effectively reduce CARM1 expression in ovarian cancer." (PMID 39964832, 2025). "In situ and patient‐derived xenograft models, inhibiting the IRE1α‐CARM1/XBP1S pathway effectively suppresses ovarian cancer both in vitro and in vivo." (PMID 39964832, 2025). "In ovarian cancer models with immunologically active CARM1 expression, the IRE1α inhibitor B‐109 synergises with immune checkpoint blockade anti‐PD1 antibodies." (PMID 39964832, 2025). "They introduced a novel strategy for treating ovarian cancer by targeting CARM1 with enhancer of zeste homologue 2 (EZH2) and ADP‐ribose polymerase (PARP) inhibitors." (PMID 39964832, 2025). "In a CARM1-expressing ovarian cancer model, the IRE1α inhibitor B-I09 increased the effectiveness of anti-PD1 therapy." (PMID 38297380, 2024). "CARM1 reprograms fatty acid metabolism transcriptionally to support ovarian cancer growth by producing monounsaturated fatty acids, supporting SCD1 inhibition as a rational strategy for treating CARM1-expressing ovarian cancer." (PMID 37377614, 2023). "There are several studies that suggested targeting CARM1 to be an effective therapeutic strategy for several diseases including acute myeloid leukemia and ovarian cancer." (PMID 37894336, 2023). "Together, we conclude that SCD1 inhibition is selective against CARM1 expression in ovarian cancer cells." (PMID 37377614, 2023). "Inhibition of the IRE1α/XBP1s pathway was effective against experimental models of ovarian cancer in a CARM1-dependent manner." (PMID 37536629, 2023). "We also employed a syngeneic mouse model generated by CARM1-expressing UPK10 mouse ovarian cancer cells." (PMID 37377614, 2023). "In all these ovarian cancer studies, CARM1 serves as a biomarker for cells amenable to EZH2 and/or PARP inhibition, rather than as a therapeutic target itself." (PMID 37536629, 2023). "The arginine methyltransferase CARM1 exhibits high expression levels in several human cancers, with the trend also observed in ovarian cancer." (PMID 37377614, 2023). "Together, we conclude that SCD1 inhibition suppresses the growth of ovarian cancers in vivo in a CARM1 status–dependent manner." (PMID 37377614, 2023). "Regardless, our results clearly demonstrated that FA metabolism represents a vulnerability of CARM1-expressing ovarian cancer, which can be therapeutically explored by targeting SCD1." (PMID 37377614, 2023). "A third study from the Zhang lab, reports that CARM1-expressing ovarian cancer cells are selectively sensitive to inhibition of the IRE1α/XBP1s pathway." (PMID 37536629, 2023).